EGFR (epidermal growth factor receptor)
Diseases named in the same sentence as EGFR in open-access papers (continued):
Sharing a sentence is not in itself a finding about the gene and the disease.
ovarian carcinoma (continued). "Stimulation of CXCR1/2 chemokine receptors by interleukin-8 has been shown to induce transient phosphorylation of EGFR, leading to the rapid activation of the p44/42 MAPK (also known as ERK1/2) in ovarian cancer cells." (PMID 22848341, 2012). "Combination treatment with the anti-EGFR-antibody Cetuximab, related tyrosine kinase inhibitors (TKI) and cytolytic NK cells was tested against different ovarian cancer cell lines and primary tumour cells cultured from patient ascites." (PMID 23109896, 2012). "Epidermal growth factor receptor (EGFR) is overexpressed in many solid tumor types, such as ovarian carcinoma." (PMID 22844475, 2012). "Inhibition of total EGFR, ERBB2, MET and AXL expression was seen in all ovarian cancer cell lines after treatment with 17-AAG in serum-containing medium for 48 hours." (PMID 21962244, 2011). "PTKs such as Her2/neu, the epidermal growth factor receptor (EGFR), and vascular endothelial growth factor (VEGF), represent potential targets for ovarian cancer, and agents targeting these molecules are already being used in the clinic for other diseases." (PMID 21541037, 2011). "In the current studies we demonstrate the simultaneous activation of multiple RTKs - including EGFR, ERBB2, MET, and/or AXL - in individual ovarian cancer cell lines and primary tumors." (PMID 21962244, 2011). "To evaluate a possible EGFR/CRM1 interaction, we incubate ovarian cancer cells with Leptomycin B, a specific CRM1 inhibitor." (PMID 21756326, 2011). "Herein, we demonstrate co-activation of multiple RTKs (EGFR, ERBB2, ERBB4, MET and/or AXL) in individual ovarian cancer cell lines and primary tumors." (PMID 21962244, 2011). "EGFR, MET, and AXL activation in the ovarian cancer lines was comparable to that in MESO924 cells, which are known to feature strong activation of these RTK." (PMID 21962244, 2011). "Consistent with this feature, EGFR and ErbB2 phosphorylation was inhibited for more than 24 h after AST1306 treatment in the SK-OV-3 human ovarian carcinoma xenograft model." (PMID 21789172, 2011). "Our results suggested that the simultaneous activation of multi-RTK (EGFR, ERBB2, ERBB4, MET and/or AXL) in individual ovarian cancer contribute to the drug resistance to individual RTK inhibitors in ovarian cancer." (PMID 21962244, 2011). "Our studies demonstrated that simultaneous activation of multi-RTKs including EGFR, ERBB2, MET, and AXL contributes to ovarian cancer cell proliferation and survival." (PMID 21962244, 2011). "The HSP90 inhibition led to the dephosphorylation and degradation of EGFR, ERBB2, ERBB4, MET and AXL in various ovarian cancer cells." (PMID 21962244, 2011). "Metronomic docetaxel chemotherapy in combination with AEE788, (a combined EGFR and VEGFR inhibitor), has shown encouraging activity in an orthotopic mouse model of ovarian cancer utilising a cell line resistant to conventional chemotherapy dosing." (PMID 24281034, 2010). "EGFR and its ligand, epidermal growth factor (EGF), play critical roles in the progression of ovarian cancer through their effects on cellular proliferation, apoptosis, angiogenesis, and metastasis." (PMID 20064265, 2010). "In ovarian cancer, metronomic docetaxel chemotherapy in combination with AEE788, a combined EGFR and VEGFR inhibitor, has shown encouraging activity in an orthotopic mouse model utilising a cell line resistant to conventional chemotherapy dosing." (PMID 19002176, 2009).
ovarian carcinoma (continued). "The results suggested that administration of NCX-4040, in combination with cisplatin, inhibited tumor growth by inducing apoptosis through downregulation of EGFR and STAT3 signaling in the cisplatin-resistant ovarian cancer xenograft in mice." (PMID 18302761, 2008). "Overexpression of EGFR (ErbB1) and HER2-neu (ErbB2) has been reported in ovarian cancer and both receptors are commonly co-expressed." (PMID 18182111, 2008). "The aim of the present study was to investigate the prognostic significance of EGFR and HER-2/neu, and their downstream targets AKT, ERK and PTEN in a large series of 232 epithelial ovarian cancer patients using the tissue microarray (TMA) platform." (PMID 18628764, 2008). "We performed an integrated analysis of EGFR and HER2-neu protein expression and gene status in a series of epithelial ovarian cancers." (PMID 18182111, 2008). "Five ovarian cancer cell lines (PE01, PE04, SKOV-3, OVCAR-5 and A2780) were investigated for their response to the EGFR-targeted inhibitor ZD 1839." (PMID 11875715, 2002). "Our findings confirmed the molecular mechanism by which COL1A1-induced upregulation of LOXL2 promotes ovarian cancer metastasis through a positive feedback loop involving EGFR-MEK-ERK-SP1, offering novel scientific insights and potential therapeutic targets for inhibiting ovarian cancer metastasis." (PMID 41807828, 2026). "We further revealed that SORL1 interacts with EGFR and FGFR4, which may contribute to maintaining the levels of EGFR and FGFR4 proteins in ovarian cancer cells." (PMID 39858026, 2025). "Among these genes, we identified sortilin-related receptor 1 (SORL1) and its role in promoting carboplatin resistance through regulating the stability of epidermal growth factor receptor (EGFR) and fibroblast growth receptor 4 (FGFR4) using ovarian cancer models in vitro and in vivo." (PMID 39858026, 2025). "In the context of ovarian cancer, such analyses can reveal how simultaneous modulation of FOXP3 and EGFR signaling may influence immune checkpoint regulators, including PD-1/PD-L1 and CTLA-4, which are crucial in tumor immune evasion." (PMID 41301890, 2025). "Clinical trials of EGFR-targeted tyrosine kinase-based inhibitors have not achieved significant benefits in patients with persistent or recurrent ovarian cancers." (PMID 39858026, 2025). "Our findings also suggest that the interaction of SORL1 with EGFR and FGFR4 may play a role in increasing the levels of EGFR and FGFR4 proteins in ovarian cancer cells." (PMID 39858026, 2025). "Furthermore, the EGFR/ERK/NFκB and EGFR/PI3K/NFκB pathways play crucial roles in cancer cell proliferation and invasion, which in turn increase IL6 and IL6R expression in chemo-resistant ovarian cancer cells." (PMID 40427188, 2025). "Clinical trials of EGFR-targeted tyrosine kinase-based inhibitors (TKIs) have not achieved significant clinical benefit in ovarian cancer." (PMID 39858026, 2025). "Moreover, the expression patterns of EGFR, Her2, FOLR1, TROP2, and TF in 25 samples of human ovarian cancer tissues was simultaneously visualized using mIF assay." (PMID 41362788, 2025). "Moreover, EGFR activation increases PAFR and LPCAT2 expression, and a significantly greater effect was noted in highly aggressive ovarian cancer CASKI cells compared to less aggressive C33A cells." (PMID 40160442, 2025). "They showed that anti-EGFR photoimmunoconjugates composed of Cetuximab and BPD could selectively accumulate in ovarian cancer metastases, enabling precise imaging and treatment." (PMID 38321470, 2024). "Detection of a panel of biomarkers (EGFR, CA125, EGFR2, folate receptor α, CD9, CD24, and EpCAM) in circulating exosomes not only identified ovarian cancer patients from control subjects but also distinguished between early- and advanced- stage ovarian cancer." (PMID 38796525, 2024).
ovarian carcinoma (continued). "GALNT14, a member of the acetylgalactosaminyltransferases family, which can regulate the stability of EGFR proteins to inhibit the EGFR/mTOR pathway, has significantly higher levels of GALNT14 in cisplatin resistance ovarian cancer tissue compared to cisplatin sensitive ovarian cancer tissue." (PMID 39192972, 2024). "Gefitinib, also known as Iressa, is an epidermal growth factor receptor (EGFR) tyrosine kinase inhibitor and a potential clinical anticancer drug, particularly with significant anti-tumor activity against non-small cell lung cancer (NSCLC) and ovarian cancer." (PMID 37875983, 2023). "Furthermore, the relationship between hyperactive EGFR signalling through STAT3 and PI3K activity together promotes high-grade ovarian cancer progression to cisplatin resistance." (PMID 37935712, 2023). "We proved for the first time that EFEMP2 could bind to EGFR to activate ERK1/2/c-Jun pathway and regulate PD-L1 expression, furthermore, PD-L1 was extremely important for EFEMP2 to promote ovarian cancer cells invasion in vitro and in vivo." (PMID 37420173, 2023). "PLC family has been reported to display a negative correlation with EGFR expression in breast, pancreatic and ovarian cancers." (PMID 36849889, 2023). "Therefore, our experiment was based on EGF activation status of EGFR, and confirmed that activation of PKG I effectively inhibited the migration and invasion of ovarian cancer cells." (PMID 36653376, 2023). "The current study revealed the suppression of higher EGF levels, as well as EGFR levels after PPE treatment to ovarian cancer cells OVCAR-3, with no impact on non-cancerous HGL5 cells." (PMID 38027211, 2023). "Activated PKG I also inhibited ovarian cancer proliferation, invasion, and metastasis in the absence of EGFR activation, but the effect was less significant than that of EGF-stimulated therapy." (PMID 36653376, 2023). "EFEMP2 could bind to EGFR to activate ERK1/2/c-Jun pathway and regulate PD-L1 expression, furthermore PD-L1 was extremely essential for EFEMP2 to promote ovarian cancer cells invasion and dissemination in vitro and in vivo." (PMID 37420173, 2023). "Moreover, compared to routine ovarian cancer cell lines, the overexpression of FAM83D protein in the highly metastatic (NM) cells was validated and showed a stronger EGFR and c-Raf phosphorylation." (PMID 37476189, 2023). "The benefits of such EGFR vIII encroached nanoparticles could be reduced by molecular targeted GTB toxicity, which ultimately helps in ovarian cancer treatment." (PMID 35363113, 2022). "We further observed a dose-dependent increase in p-ERK, p-90RSK and p-Akt by up to 2- to threefold in fentanyl-treated ovarian cancer cells (p < 0.001), suggesting the activation of MEK/ERK and PI3K/Akt which are the major downstream signaling pathways of EGFR." (PMID 35999506, 2022). "Estrogens binding to GPER induce ovarian cancer cell proliferation through activation of multiple downstream signals such as ERK (extracellular-signal-regulated kinase), PI3K (phosphoinositide 3-kinase), and EGFR (epidermal growth factor receptor)." (PMID 36558071, 2022). "Additionally, through EGFR signaling, ST3GAL1 overexpression can encourage the migratory and peritoneal spread of ovarian cancer cells." (PMID 36547200, 2022).
ovarian carcinoma (continued). "Our present study employed SKOV3, A2780 ovarian cancer cells, and xenograft model in vitro and in vivo to test the anticancer effect of SK and identified a novel mechanism by which SK induced apoptosis via GPER-mediated EGFR/PI3K/AKT downregulation." (PMID 36248433, 2022). "In summary, SK may affect the apoptosis of ovarian cancer cells through GPER/EGFR/PI3K/AKT, and GPER may be a key target of SK in ovarian cancer cell apoptosis." (PMID 36248433, 2022). "Moreover, we found that miR-146b exerts a dual inhibitory effect on the EGFR and IL-6-STAT3 pathways pathway in ovarian cancer cells." (PMID 34369236, 2021). "Very promising results were obtained when the GE11-conjugated doxorubicin filled liposomes (GE11-PS-Dox) were used to treat ovarian cancer xenograft bearing mice, indicating GE11-guided drug targeting as an alternative for treatment of EGFR overexpressing ovarian cancers." (PMID 33918106, 2021). "We then measured the expression of EGFR and IL-6-STAT3 in ovarian cancer cell lines." (PMID 34369236, 2021). "A previous study demonstrated that dual inhibition of the EGFR and STAT3 pathways could lead to the simultaneous attenuation of multiple survival pathways in ovarian cancer." (PMID 34369236, 2021). "We further found that EGFR and IL-6-STAT3 expression was upregulated in ovarian cancer cells." (PMID 34369236, 2021). "EGFR could activate a variety of downstream pathways, such as the ERK, AKT and STAT3 pathways, in ovarian cancer cells." (PMID 34369236, 2021). "We investigated the relationship between the three subtypes and various well‐known oncogenic genes and tumour suppressors in ovarian cancer from cBioPortal and found EIF5A2 (P < 0.001), FGF1 (P < 0.001) and EGFR (P = 0.002) were highly expressed in the CAFs‐immune subtype." (PMID 33522069, 2021). "ALKBH5 is elevated in epithelial ovarian cancer, silencing of ALKBH5 enhances the autophagy signaling and inhibits the proliferation and invasion abilities of ovarian cancer cells by reducing EGFR/PI3K/AKT signaling activity through physically interacting with HuR204." (PMID 33611339, 2021). "None of the designed EGFR inhibitors to date have shown promising results in clinical trials for successful treatment of patients with ovarian cancer." (PMID 33936221, 2021). "Since we already demonstrated that EGFR and Bcl-xL are direct targets of miR-491-5p in IGROV1-R10 ovarian cancer cells, and that the most striking phenotype upon miR-491-5p transfection is the induction of cell death, we did expect to identify pathways related to cell death and/or MAPK." (PMID 34439123, 2021). "Combined blockade of EGFR and IL-6-STAT3 pathways by miR-146b might be a strategy for improving the clinical benefit of targeting the EGFR pathway in ovarian cancer patients in the future." (PMID 34369236, 2021). "EGFR has been shown to modulate the ERK-pathway in many cancer types, including ovarian cancer." (PMID 32231055, 2020). "EGFR inhibitors (Gefitinib, PD153035 and AG1478), MAPK antagonist (PD98059) and PI3K inhibitor (LY294002) have shown their potential to inhibit survivin in breast, lung, pancreatic, colon and ovarian cancer cell lines." (PMID 32691369, 2020). "ALKBH5 was shown to regulate the processing of miR-7 in a HuR dependent manner in ovarian cancer and to affect the expression of miR-7 target gene EGFR, which gave us a hint that ALKBH5 might serve as a biomarker or target in the anti-EGFR chemotherapy." (PMID 32209098, 2020).
ovarian carcinoma (continued). "In ovarian cancer models, it has been shown that the stimulation of PAFR transactivates EGFR." (PMID 33392068, 2020). "The combination of MTOR inhibitors, and EGFR, RTK, PI3K signaling inhibitors might be synergy to inhibit ovarian cancer development." (PMID 32958005, 2020). "To further characterize the biological effects of anti-EGFR sensitization, we evaluated the expression of stress-induced ligands and MHC class I molecules as well as the release of different cytokines by sensitized ovarian cancer cells." (PMID 31546690, 2019). "For example, the addition of bevacizumab, a monoclonal antibody against vascular endothelial growth factor (VEGF), or cetuximab, a monoclonal antibody against epidermal growth factor receptor (EGFR), was found to increase survival rates in patients with ovarian cancer in chemotherapy." (PMID 31355133, 2019). "Furthermore, CXCR-1 and CXCR-2 were also demonstrated to be strongly expressed in ovarian cancer cell lines, and to activate mitogen-activated protein (MAP) kinase via EGFR, contributing to cell migration and proliferation." (PMID 31703453, 2019). "Moreover, CA-125 with CA 19–9, EGFR, G-CSF, Eotaxin, IL-2R, cVCAM, MIF improved the sensitivity with 98.2 % and specificity of 98.7% in early stage detection of ovarian cancer." (PMID 31867451, 2019). "In this study, we provide evidence that activity of ADAM17 and expression as well as shedding of the ADAM17 substrate AREG increase subsequently to chemotherapeutic treatment thus playing an important role in EGFR and ERK dependent chemo-sensitization of ovarian cancer cells." (PMID 29662625, 2018). "Unfortunately, none of EGFR inhibitors (erlotinib, cetuximab or lapatinib) showed promising results in clinical trials investigating its efficacy in ovarian cancer treatment." (PMID 29249039, 2018). "For example, some data favored EGFR as a reliable marker of survival or responsiveness to therapy but others did not, and some reports indicated that using EGFR inhibitors in ovarian cancer patient had not shown favorable clinical outcomes." (PMID 29510732, 2018). "The aim of the present study was to determine the relative expression, cellular location, and prognostic significance of HER-family members, the EGFR mutant (EGFRvIII) c-MET, IGF-1R and the cancer stem cell biomarker CD44 in 60 patients with FIGO stage III and IV ovarian cancer." (PMID 29731973, 2018). "An immunohistochemical study showed that EGFR could be found in 61% of CCC, and the overexpression of EGFR might be related to chemotherapy resistance and poor prognosis of ovarian cancer." (PMID 29843765, 2018). "Moreover, evidence on the prognostic value of EGFR and HER2 with respect to survival is still inconclusive in ovarian cancer." (PMID 28187748, 2017). "In addition, knockdown of GALNT6 reduced Tn antigen expression on EGFR and decreased the phosphorylation of EGFR in ovarian cancer cells, suggesting that GALNT6 affects ovarian cancer progression by modifying EGFR activity." (PMID 28388560, 2017). "For example, the EGFR inhibitor erlotinib sensitized EGFR-overexpressing TNBC cells to doxorubicin, whereas low dose metformin or the TopoI inhibitor SN38 increased the DNA damage response in ovarian cancer cells." (PMID 28187446, 2017). "The in vitro specificity of the radiolabelled peptide for binding to EGFR was determined in SKOV3, A549, and MCF-7 cell lines, of which SKOV3 ovarian carcinoma cells accumulated higher amount of the radiolabeled peptide and was used for in vivo tumor targeting in nude mice." (PMID 28464952, 2017). "The over-expression of EGFR was reported to be involved in EMT activation via the Akt/Erk1/2 pathways, inducing Vimentin expression and dowregulation of E-cadherin favoring invasiveness in ovarian cancer cells." (PMID 26910918, 2017).